CD58 (CD58 molecule)
Description:
Ligand of the T-lymphocyte CD2 glycoprotein. This interaction is important in mediating thymocyte interactions with thymic epithelial cells, antigen-independent and -dependent interactions of T-lymphocytes with target cells and antigen-presenting cells and the T-lymphocyte rosetting with erythrocytes. In addition, the LFA-3/CD2 interaction may prime response by both the CD2+ and LFA-3+ cells.
Synonyms: Ag3; LFA3; LFA-3
Tractability: Antibody: its Gene Ontology location is reachable by antibodies, with high confidence; UniProt places it where antibodies can reach, with medium confidence; UniProt predicts a signal peptide or a membrane-spanning region. PROTAC: ubiquitination databases record sites on it; its protein half-life has been measured; a small molecule that binds it is known.
Target class: Other membrane protein
Gene: Protein-coding gene on chromosome 1 (116,514,534 to 116,571,039, reverse strand). Ensembl gene ENSG00000116815.
Subcellular location: Cell membrane (Isoform 1)
Pathways (Reactome):
Hemostasis: Cell surface interactions at the vascular wall
Immune System: Neutrophil degranulation
Gene Ontology:
Molecular function: protein binding; signaling receptor binding
Biological process: cellular response to tumor necrosis factor; cellular response to type II interferon; heterotypic cell-cell adhesion; positive regulation of interleukin-8 production; cell-cell adhesion; immune response
Cellular component: cell surface; extracellular exosome; membrane; ficolin-1-rich granule membrane; plasma membrane; secretory granule membrane
Genetic constraint (gnomAD): Loss-of-function variants: 7 observed, 17.39 expected, observed/expected ratio (o/e) 0.4, 90% interval 0.23 to 0.76. The upper end of that interval is the gene's LOEUF score, 0.76, which puts it in group 3 of 6, group 1 being the genes least tolerant of losing a copy. Missense variants: 207 observed, 228.85 expected, observed/expected ratio (o/e) 0.9, 90% interval 0.81 to 1.01. Synonymous variants: 97 observed, 79.41 expected, observed/expected ratio (o/e) 1.22, 90% interval 1.03 to 1.45.
Homologues: Orthologues: chimpanzee CD58 (97% identical), macaque CD58 (82% identical), dog CD58 (45% identical), pig CD58 (38% identical).
Diseases named in the same sentence as CD58 in open-access papers:
CD58 is named in the same sentence as 121 diseases in open-access papers, as found by Europe PMC text mining. Sharing a sentence is not in itself a finding about the gene and the disease. The quoted sentences say what the papers report.
melanoma (13 papers, 2012 to 2025). A malignant, usually aggressive tumor composed of atypical, neoplastic melanocytes. "Beyond T cell interactions, CD58 is indispensable for NK cell-mediated cytotoxicity, and loss of CD58 in melanoma and B-lymphoblastic leukemia lines confers resistance to NK cell attack." (PMID 41295262, 2025). "It was reported that CD58 loss upregulated PDL1 expression in melanoma, in addition, ALKBH5 deficiency enriched m6A modification in the 3’UTR region of PDL1 mRNA and promoted its degradation in intrahepatic cholangiocarcinoma." (PMID 38589927, 2024). "CD58 mutation or downregulated expression is common in melanoma and hematological tumors, and downregulation of CD58 is associated with immune evasion in melanoma and that disruption of CD58 in tumor cells confers functional impairment of CAR T cells." (PMID 38589927, 2024). "Mechanistic studies with expanded TILs have demonstrated that CD58-knockout melanoma cells are less susceptible to killing by TILs and NK cells, which is similar to our observations with CAR T cells." (PMID 35881486, 2022). "scRNA-Seq of melanoma patient tumor ecosystems identified a baseline gene signature that included downregulation of CD58 as associated with T cell exclusion (cold tumors) and intrinsic resistance to ICB therapy." (PMID 35881486, 2022). "CD58 loss induced immune evasion in different co-culture models with CTLs, and the PD-L1 expression was elevated in CD58-knockout melanoma cells." (PMID 34168659, 2021). "High expression of CD58 has been shown to predict a more favorable prognosis in melanoma and ductal A/B breast cancer." (PMID 40365344, 2025). "Further co-culture data indicated that the deletion of CD58 in melanoma cells gave resistance to cytotoxicity mediated by T cells and NK cells." (PMID 40365344, 2025). "Previous study has shown that CMTM6 is critical for CD58 stability and upregulation of PDL1 upon CD58 loss in melanoma." (PMID 38589927, 2024). "Particularly, we observed that CD58 staining was largely restricted to areas with CMTM6 expression in 74 out of 88 melanomas." (PMID 37683639, 2023). "To assess the association between CMTM6 and CD58 expression and response to ICB therapies, we analyzed tumor biopsies obtained from 88 patients with advanced melanoma." (PMID 37683639, 2023). "Independently, expression levels of CD58 mRNA were significantly lower in melanoma patients that failed ICB therapy compared with treatment-naive patients." (PMID 35881486, 2022). "A recent study reported that the surface expression of CD58 was strongly reduced in tumor cells of melanoma patients with ICB resistance compared with that of untreated patients." (PMID 34168659, 2021). "Thus, elevating CD58 expression is likely to contribute to the alleviation of ICB resistance in melanoma patients." (PMID 34168659, 2021). "However, in melanoma and ductal A/B breast cancer, CD58 functions as an anti-tumor effector." (PMID 40365344, 2025). "Also, PD-L1 was upregulated in CD58-knockout melanoma cells." (PMID 34423049, 2021). "In addition, CD58 knockdown could enhance the expression of co-inhibitory PD-L1 in melanoma cells, which may result in the dysfunction of T cells by interacting with PD-1 on T cells in the tumor microenvironment." (PMID 34193136, 2021). "Besides, our results demonstrate a positive correlation between elevated levels of CMTM6 and CD58 expression in tumor cells and the clinical benefits in ICB treatment among a cohort of melanoma patients, suggesting potential clinical significance." (PMID 37683639, 2023). "To validate the regulatory role of CMTM6 in CD58 and PD-L1 expression, we conducted CMTM6 deletion and reconstitution in cell lines derived from multiple cancer types, including 8505C thyroid cancer cells, A375 melanoma cells, and RKO colorectal cancer cells." (PMID 37683639, 2023).
melanoma (continued). "We found that CD58 and CD155, which function as binding partners for the adhesion molecules CD2 and CD226, respectively, are broadly expressed in cell lines derived from human melanomas or B cell tumors." (PMID 29707134, 2018). "Hence, combining melanoma antigen-specific TCRs with CD2::CD28 chimeric receptors might have potential in adoptive T cell therapy, since melanoma cells were shown to have high expression of CD58." (PMID 29707134, 2018). "To investigate the relationship between CMTM6 and CD58 expression in human cancers, we conducted immunohistochemistry (IHC) analysis on 88 melanoma samples and 102 colon cancer samples using validated antibodies for CMTM639 (data not shown) or CD58." (PMID 37683639, 2023).
lymphoma (12 papers, 2014 to 2025). A malignant (clonal) proliferation of B- lymphocytes or T- lymphocytes which involves the lymph nodes, bone marrow and/or extranodal sites. "In hematologic tumors, CD58 is frequently present as an antitumor effector, and CD58 deficiency is associated with a poor prognosis in leukemia and lymphoma." (PMID 40365344, 2025). "EZH2 GOF mutations also induce CD58 epigenetic silencing in lymphoma cells, associated with a decreased NK cell activation, suggesting that lymphoma B cells harboring EZH2 mutations can escape both T cell and NK cell lysis." (PMID 38022603, 2023). "Aberrant expression of CD58 has been demonstrated to exert a significant impact on the prognosis of hematological tumors, including leukemia and lymphoma." (PMID 40365344, 2025). "B-lymphoblastic leukemia/lymphoma with TCF3::PBX1 fusion has also been reported to overexpress CD58 and CD81 when compared with cases of B-lymphoblastic leukemia/lymphoma without cytogenetic alterations or with other cytogenetic abnormalities." (PMID 40227608, 2025). "We showed that CD2 on T cells is associated with directional migration and that the interaction between CD2 on T cells and CD58 on lymphoma cells accelerates killing and serial killing." (PMID 35881486, 2022). "We also identified frequent genetic alterations in immune surveillance genes (B2M and CD58), suggesting immune escape contributes to lymphoma relapse." (PMID 25123191, 2014). "The absence of CD58 correlates with immune evasion and pharmacological resistance in hematological malignancies, including leukemia and lymphoma, and is a unique biomarker for forecasting clinical outcomes in the new era of immunotherapy." (PMID 40365344, 2025). "Besides, EZH2 inhibitor can restore CD58 expression on the surface of lymphoma cells, which in turn increases IFN-γ secretion of T/NK cells against lymphoma cells." (PMID 34168659, 2021).
multiple sclerosis (12 papers, 2010 to 2024). A progressive autoimmune disorder affecting the central nervous system resulting in demyelination. "We conducted a Mendelian randomization analysis leveraging the cis-instrumental variable for CD58 in the International Multiple Sclerosis Genetics Consortium and found additional evidence for a potential causal role of circulating CD58 in MS development." (PMID 39316441, 2024). "rs1414273 is located within the miR-548ac stem-loop sequencing in the first intron of the CD58 gene, which has shown a strong linkage disequilibrium with the Multiple Sclerosis (MS)-associated haplotype." (PMID 34777472, 2021). "We previously reported an intronic Alu at CD58 mapping near a GWAS signal for multiple sclerosis (MS) risk (P = 3 × 10−16)." (PMID 30418605, 2019). "Association (allelic model) between multiple sclerosis and CD58 gene polymorphism alleles rs12044852 (p = 0.410), rs2300747 (p = 0.881) and rs1335532 (p = 0.407) were indistinct." (PMID 32257069, 2019). "This pilot study was conducted to explore the association between CD58 polymorphism and multiple sclerosis among the Malay population in Malaysia." (PMID 32257069, 2019). "Polymorphisms in the CD58 gene have recently been reported to be related to the risk of multiple sclerosis through alterations in the processing of microRNA62." (PMID 30076325, 2018). "The CD58 protective allele has higher mRNA expression in lymphoblastic cell lines and mononuclear cells from multiple sclerosis patients than the susceptible allele does." (PMID 26438525, 2015). "The CD2/CD58/CD48 pathway is associated with the human autoimmune diseases multiple sclerosis and rheumatoid arthritis and with a model of murine lupus." (PMID 26438525, 2015). "In a previous genome-wide association study, cluster of differentiation 58 (CD58) region was found to be susceptible for the risk of multiple sclerosis (MS) in Caucasian, and the association between CD58 variants and MS was replicated in Americans." (PMID 24655566, 2014). "A cis-pQTL for CD58 was associated with multiple sclerosis (MS) as well as WBC count." (PMID 39316441, 2024). "In addition, alterations in CD2/CD58 signaling are associated with multiple sclerosis and rheumatoid arthritis." (PMID 37596785, 2024). "Reduced CD58 expression is associated with risk for developing multiple sclerosis." (PMID 30418605, 2019). "Moreover, the CD2/CD58 pathway is associated with the human autoimmune diseases, multiple sclerosis, and rheumatoid arthritis, and the CD2/CD48 pathway is associated with a model of murine lupus." (PMID 26438525, 2015). "We found concordant associations across clinical diagnoses and laboratory measurements, elucidating disease pathways, including a cis-pQTL associated with circulating CD58, WBC count, and multiple sclerosis." (PMID 39316441, 2024). "These alleles are analogous to the protective allele in human multiple sclerosis, suggesting that higher levels of CD2/CD58 expression and function have a protective effect against autoimmunity." (PMID 26438525, 2015). "Association of non-human leukocyte antigen gene, CD58, with multiple sclerosis has been reported in several populations but is unclear among Southeast Asians." (PMID 32257069, 2019). "Recent association studies in multiple sclerosis (MS) have identified and replicated several single nucleotide polymorphism (SNP) susceptibility loci including CLEC16A, IL2RA, IL7R, RPL5, CD58, CD40 and chromosome 12q13–14 in addition to the well established allele HLA-DR15." (PMID 20368992, 2010). "In a replication GWAS study conducted by The Australia and New Zealand Multiple Sclerosis Genetics Consortium (ANZgene) which analysed more than 1500 MS cases, it was reported that SNP rs1335532 of CD58 is one of the non-HLA SNPs that was highly associated with MS." (PMID 32257069, 2019).
multiple sclerosis (continued). "The impact of the CD58 gene polymorphism was not prominent in this pilot study, implying that genetic composition contributing to multiple sclerosis may be different between different populations, thus results in a heterogeneity of disease manifestation and distribution." (PMID 32257069, 2019). "Dysfunction of CD58 and CD2 in humans results in various diseases, such as multiple sclerosis, rheumatic arthritis, and psoriasis." (PMID 29904386, 2018). "Moreover, CD58 and CD2 have attracted attention because of their involvement in various diseases, such as rheumatic arthritis, multiple sclerosis, colorectal cancer, and diffuse large B cell lymphoma." (PMID 29904386, 2018).
autoimmune disease (11 papers, 2015 to 2025). A disorder resulting from loss of function or tissue destruction of an organ or multiple organs, arising from humoral or cellular immune responses of the individual to their own tissue constituents. "Recently, a GWAS study has revealed that CD58 is a shared genetic susceptibility locus between SLE and PBC, and rs10924104 is associated with the regulating of CD58 expression and the intensity of autoimmune disease susceptibility." (PMID 38464525, 2024). "Previous studies have demonstrated that soluble CD58 can block the interaction of CD2/CD58, thereby playing a therapeutic role in inflammation and autoimmune diseases." (PMID 38550602, 2024). "RRA discovery study suggested that CD160 was the most significant gene aberrantly expressed in autoimmune diseases (Adjusted P = 5.9E-12), followed by CD58 (Adjusted P = 5.7E-06) and CD244 (Adjusted P = 9.5E-05)." (PMID 30842773, 2019). "CD2 and CD58 molecules have been shown to be important in inflammatory and autoimmune diseases such as rheumatoid arthritis (RA)." (PMID 26111183, 2015). "Findings from the RRA discovery study suggested that CD160 was the most significant gene aberrantly expressed in autoimmune diseases (Adjusted P = 5.9E-12), followed by CD58 (Adjusted P = 5.7E-06), CD244 (Adjusted P = 9.5E-05), LGALS9 (Adjusted P = 0.001) and CD27 (Adjusted P = 0.005)." (PMID 30842773, 2019). "Genome-wide association studies (GWASs) have also identified several non-HLA genetic variants linked to MS, including those in the interleukin-7 receptor (IL7RA), interleukin-2 receptor (IL2RA), CD58, and CLEC16A genes, indicating a shared genetic foundation with other autoimmune diseases." (PMID 40724862, 2025). "Lower expression of Treg with higher expression of CD58 (LFA-3) was found in the autoimmune diseases when compared with the non-immune and control groups." (PMID 29706856, 2018). "However, findings from the RRA validation study suggested that CD58 was not aberrantly expressed in autoimmune diseases (Adjusted P = 0.99)." (PMID 30842773, 2019).
leukemia (11 papers, 2021 to 2025). A malignant (clonal) hematologic disorder, involving hematopoietic stem cells and characterized by the presence of primitive or atypical myeloid or lymphoid cells in the bone marrow and the blood. "Leukemia patients with poor prognosis frequently lack the expression of CD58, while the higher expression of CD58 is strongly associated with longer survival time." (PMID 34168659, 2021). "Likewise, CD58 has also been identified in a recent CRISPR–Cas9 loss of function screen performed in a CD19 CAR T cell-leukemia cell co-culture model." (PMID 36189315, 2022). "Seven leukemia-associated immunophenotype pattern (LAIP) markers, CD9, CD44, CD58, CD73, CD81, CD86, and CD123, were also included in the diagnostic panel." (PMID 39371707, 2024). "The use of the CD81/CD58 ratio as the discriminating marker enhances the difference between leukemia lymphoblasts and hematogones with high sensitivity and specificity in patients with BCP-ALL." (PMID 34168659, 2021). "Among them, more datasets support the lower expression of CD58 in leukemia, lung cancer, and sarcoma, while its expression was significantly increased in bladder cancer, brain and CNS cancer, and pancreatic cancer, compared with corresponding normal tissues." (PMID 34193136, 2021). "Nonetheless, CD58 expression in leukemia cells may be markedly down-regulated following induction chemotherapy, so this issue needs to be noted when employing CD58 for MRD prognostic monitoring." (PMID 40365344, 2025). "CD58 and ADAM10 have been implicated in leukemia progression and chemoresistance; however, their specific roles in acute lymphoblastic leukemia (ALL) and chronic lymphocytic leukemia (CLL), particularly under chemotherapeutic pressure, remain insufficiently characterized." (PMID 40746920, 2025). "Leukemia engraftment in immune-deficient mice did not require the expression of CD58 or CD97, which were mostly co-expressed with CD19." (PMID 36673136, 2023). "CD58 is often expressed higher on leukemia B lymphoblasts than on normal B-cell progenitors." (PMID 36611312, 2022). "The leukemia-containing clusters were found to have a low expression of CD48 and CD58, the genes coding for activating ligands that bind CD2." (PMID 35349491, 2022). "In patient 1, in whom most of the expanded and persistent NK cells exhibited a mature cytotoxic CD56dimCD16+ phenotype, the absence of expression of CD48 and CD58 on relapsed leukemia could suggest a resistance mechanism." (PMID 35349491, 2022).
rheumatoid arthritis (7 papers, 2015 to 2025). A chronic, systemic autoimmune disorder characterized by inflammation in the synovial membranes and articular surfaces. "Previous research has linked CD58 variations to other autoimmune disorders, including Rheumatoid Arthritis (RA) and Systemic Lupus Erythematosus (SLE), suggesting common genetic determinants and immunological dysregulation across these diseases." (PMID 39810445, 2025). "They systematically examined 370 SNPs from 179 independent loci with P < 1 × 10− 3, and three gene regions in CD28, PRDM1 and CD2/CD58 were identified that were closely related to rheumatoid arthritis." (PMID 31842750, 2019). "In rheumatoid arthritis, CD58 is known to be overexpressed, and this leads to recruitment of T cells at the joints, causing inflammation." (PMID 30227746, 2018). "Here, for the first time, we employed PLA to visualize the interaction between CD2 and CD58 proteins that are present on two different cells, Jurkat cells and human fibroblast-like synoviocyte-rheumatoid arthritis (HFLS-RA) cells, respectively." (PMID 30227746, 2018).
breast carcinoma (6 papers, 2006 to 2025). "At a study of the mechanism that NK-mediated cytotoxicity to breast cancer targets, unexpectedly, anti-CD58 mAb failed to inhibit NK-mediated killing but instead mediated the enhanced cytotoxicity associated with CD58 expression, albeit CD2 blockade mildly reduced cytotoxicity." (PMID 34168659, 2021). "As sgRNAs were unavailable for CD2, we alternatively knocked out CD58, the cognate ligand for CD2, in MDA-MB-231 breast cancer cells." (PMID 40955669, 2025).